RBPJ (recombination signal binding protein for immunoglobulin kappa J region)
Description:
Transcriptional regulator that plays a central role in Notch signaling, a signaling pathway involved in cell-cell communication that regulates a broad spectrum of cell-fate determinations. Acts as a transcriptional repressor when it is not associated with Notch proteins. When associated with some NICD product of Notch proteins (Notch intracellular domain), it acts as a transcriptional activator that activates transcription of Notch target genes. Probably represses or activates transcription via the recruitment of chromatin remodeling complexes containing histone deacetylase or histone acetylase proteins, respectively. Specifically binds to the immunoglobulin kappa-type J segment recombination signal sequence. Binds specifically to methylated DNA. Binds to the oxygen responsive element of COX4I2 and activates its transcription under hypoxia conditions (4% oxygen). Negatively regulates the phagocyte oxidative burst in response to bacterial infection by repressing transcription of NADPH oxidase subunits (By similarity).
Synonyms: RBP-J; RBP-JK; IGKJRB; IGKJRB1; RBPJK; RBPSUH; SUH; KBF2; CBF1; AOS3; CBF-1; RBP-J kappa; csl
Tractability: Small molecule: it has a binding pocket of medium quality. PROTAC: ubiquitination databases record sites on it; its protein half-life has been measured; a small molecule that binds it is known.
Target class: Transcription factor
Gene: Protein-coding gene on chromosome 4 (26,163,455 to 26,435,131, forward strand). Ensembl gene ENSG00000168214.
Subcellular location: Nucleus; Cytoplasm
Subcellular location (Human Protein Atlas): Nucleoplasm
Pathways (Reactome):
Signal Transduction: NOTCH1 Intracellular Domain Regulates Transcription; NOTCH2 intracellular domain regulates transcription; NOTCH3 Intracellular Domain Regulates Transcription; NOTCH4 Intracellular Domain Regulates Transcription; Pre-NOTCH Transcription and Translation
Developmental Biology: Differentiation of naive CD4+ T cells to T helper 2 cells (Th2 cells); Formation of paraxial mesoderm; Regulation of gene expression in late stage (branching morphogenesis) pancreatic bud precursor cells; Somitogenesis
Disease: Constitutive Signaling by NOTCH1 HD+PEST Domain Mutants; Constitutive Signaling by NOTCH1 PEST Domain Mutants
Gene expression (Transcription): Notch-HLH transcription pathway; RUNX3 regulates NOTCH signaling
Gene Ontology:
Molecular function: DNA-binding transcription activator activity, RNA polymerase II-specific; DNA-binding transcription factor binding; protein binding; RNA polymerase II cis-regulatory region sequence-specific DNA binding; RNA polymerase II-specific DNA-binding transcription factor binding; sequence-specific DNA binding; DNA binding; DNA-binding transcription factor activity; DNA-binding transcription factor activity, RNA polymerase II-specific; chromatin binding
Biological process: heart development; negative regulation of DNA-templated transcription; negative regulation of transcription by RNA polymerase II; Notch signaling pathway; positive regulation of DNA-templated transcription; positive regulation of transcription by RNA polymerase II; positive regulation of transcription of Notch receptor target; regulation of generation of precursor metabolites and energy; angiogenesis; aortic valve development; atrioventricular canal development; blood vessel endothelial cell fate specification; blood vessel lumenization; blood vessel remodeling; cardiac left ventricle morphogenesis; cardiac muscle cell myoblast differentiation; dorsal aorta morphogenesis; endocardium morphogenesis; epithelial to mesenchymal transition; epithelial to mesenchymal transition involved in endocardial cushion formation; labyrinthine layer blood vessel development; negative regulation of cold-induced thermogenesis; negative regulation of ossification; outflow tract morphogenesis; positive regulation of BMP signaling pathway; and 13 more
Cellular component: CSL-Notch-Mastermind transcription factor complex; cytoplasm; MAML1-RBP-Jkappa- ICN1 complex; nucleolus; nucleoplasm; nucleus; transcription repressor complex; chromatin; transcription regulator complex
Genetic constraint (gnomAD): Loss-of-function variants: 7 observed, 49.3 expected, observed/expected ratio (o/e) 0.14, 90% interval 0.08 to 0.27. The upper end of that interval is the gene's LOEUF score, 0.27, which puts it in group 1 of 6, group 1 being the genes least tolerant of losing a copy. Missense variants: 253 observed, 489.62 expected, observed/expected ratio (o/e) 0.52, 90% interval 0.47 to 0.57. Synonymous variants: 162 observed, 168.63 expected, observed/expected ratio (o/e) 0.96, 90% interval 0.85 to 1.09.
Homologues: Orthologues: dog RBPJ (99% identical), chimpanzee RBPJ (99% identical), macaque RBPJ (99% identical), mouse Rbpj (99% identical), pig RBPJ (98% identical), rat Rbpj (98% identical), rabbit RBPJ (98% identical), guinea pig RBPJ (97% identical), tropical clawed frog rbpj (96% identical), zebrafish rbpja (91% identical), zebrafish rbpjb (91% identical), Drosophila melanogaster Su(H) (76% identical). Paralogues in human: RBPJL (51% identical).
Diseases named in the same sentence as RBPJ in open-access papers:
RBPJ is named in the same sentence as 156 diseases in open-access papers, as found by Europe PMC text mining. Sharing a sentence is not in itself a finding about the gene and the disease. The quoted sentences say what the papers report.
breast cancer (23 papers, 2012 to 2025). A primary or metastatic malignant neoplasm involving the breast. "The authors concluded that RBPJ is unlikely to play a primary pathogenic role—particularly given that anti-RBPJ antibodies have also been reported in unrelated conditions such as breast cancer." (PMID 41226806, 2025). "A recent study focused on the frequent RBPJ copy number loss and diminished RBPJ protein expression in a significant minority of several types of carcinoma, mainly breast carcinomas." (PMID 36627893, 2022). "N1ICD/RBPJ was showed to physically interact with ESR1 in breast cancer cells, forming a common complex bound to DNA, which enables ESR1-dependent activation of Notch1-mediated signaling." (PMID 40506655, 2025). "In this study, we demonstrated that fidaxomicin was identified as a potential small molecule inhibitor of RBPJ, eventually inhibiting Notch signaling in breast cancer cells." (PMID 35631382, 2022). "RBP-Jk can act as a transcriptional repressor and loss of the RBPJ gene promotes the growth of human breast cancer cells by de-repressing target gene promoters in a Notch-independent manner." (PMID 36358826, 2022). "Finally, an FDA-approved antibiotic, fidaxomicin, was identified as a potential RBPJ inhibitor, and its ability to block RBPJ-dependent transcription and thereby inhibit breast cancer growth was experimentally verified." (PMID 35631382, 2022). "In current study we analyzed six previously identified medullary breast carcinoma autoantigens including LGALS3BP, RAD50, FAM50A, RBPJ, PABPC4, LRRFIP1 with cancer restricted serological profile in different histological types of breast cancer." (PMID 23181716, 2012). "In mice, NOTCH4 activation in the ductal epithelium required RBPjκ for physiological alveolar development, but not for breast cancer development, suggesting Notch4 functions via both canonical and non-canonical pathway in the breast endothelium." (PMID 34665379, 2022). "Thus, during this study we described for the first time expression patterns of 6 potential MBC-associated antigens, including LGALS3BP, RAD50, FAM50A, RBPJ, PABPC4, LRRFIP1 in different histological types of breast carcinomas and non-cancerous breast tissues by immunohistochemical analysis." (PMID 23181716, 2012). "The results also showed that siRNA of RBPJκ (siRBPJκ) obviously reduced the mRNA expression of RBPJκ but did not affect cell migration and did not abolish the effect of DAPT on the migration in breast cancer cells." (PMID 31057403, 2019).
glioma (17 papers, 2016 to 2025). A benign or malignant brain and spinal cord tumor that arises from glial cells (astrocytes, oligodendrocytes, ependymal cells). "As one of RBPJ’s target genes is often mutated in glioma, its downregulation diminished the malignant phenotype." (PMID 36293193, 2022). "Here in P1 glioma cells, experimentally reducing RBPJ expression using lentiviral shRNAs resulted in decreased ORC6 expression at both the mRNA and protein levels." (PMID 38971772, 2024). "The results showed that RBPJ siRNA resulted in the most significant decrease in ORC6 mRNA expression within P1 glioma cells." (PMID 38971772, 2024). "Subsequently, P1 glioma cells received treatment of lentivirus containing RBPJ shRNA (shRBPJ-Sq1 and shRBPJ-Sq2, using different sequences), leading to the establishment of stable cells after selection." (PMID 38971772, 2024). "Our study explored the potential mechanism responsible for the increased expression of ORC6 in human glioma, highlighting the pivotal role of RBPJ as a crucial transcription factor." (PMID 38971772, 2024). "Altogether, RBPJ-driven ORC6 overexpression promotes glioma cell growth, underscoring its significance as a promising therapeutic target." (PMID 38971772, 2024). "Together, RBPJ-driven ORC6 overexpression promotes glioma cell growth, underscoring its significance as a promising therapeutic target." (PMID 38971772, 2024). "In contrast to P1 glioma cells with scramble control shRNA (“shC”), cells with shRBPJ displayed a remarkable decrease in RBPJ mRNA and protein expression, accompanied by a significant reduction in ORC6 mRNA and protein expression." (PMID 38971772, 2024). "In this report it was shown that metabolic stress resulted in a cyclin F-dependent polyubiquitylation of RBPJ in glioma cells, followed by proteasomal degradation." (PMID 36293193, 2022). "In contrast, a half-life of ten hours or more was measured for RBPJ in other cell types (human umbilical vein endothelial cells, U251 glioma cells) even upon induction of proteolysis by VEGF treatment or by metabolic stress." (PMID 36293193, 2022). "Since being discovered, FBXO1 has been confirmed to be closely connected to cancer in that FBXO1 inhibits tumorigenesis of gliomas owing to interacting with the recombination signal binding protein for immunoglobulin kappa J region (RBPJ) for degradation." (PMID 36362432, 2022). "For example, metabolic stress in glioma cells resulted in the induction of cyclin F in a FOXO1-dependent manner that leads to RBPJ proteolysis." (PMID 36293193, 2022). "Accordingly, the expression of some NOTCH target genes is downregulated in NOTCH/RBPJ mutant gliomas, indicating pathway inactivation." (PMID 33076453, 2020). "Blocking NOTCH signaling or RBPJ reduced clonogenic potential in tumor-sphere assays and engraftment capacity in glioma xenograft models." (PMID 33076453, 2020). "Contrarily, P1 glioma cells were treated with lentivirus carrying the RBPJ-expressing construct." (PMID 38971772, 2024). "This hypothesis is supported by an in vivo CRISPR screen that identified Notch1 among potential tumor suppressors in glioma, and is further in line with the occurrence of NOTCH1, NOTCH2, and RBPJ inactivating mutations and/or reduced Notch signaling activity in human glioma subtypes." (PMID 36358826, 2022). "Significantly, ChIP assay results demonstrated a significant increase in the binding between the RBPJ protein and the presumed ORC6 promoter region’s binding cites (GCTGGGAAGG, from JASPAR database) within glioma tissues obtained from local patients." (PMID 38971772, 2024). "Significantly, our results discovered strengthened binding between the RBPJ protein and the ORC6 promoter region across various glioma tissues and also in primary/immortalized glioma cells." (PMID 38971772, 2024). "Inactivating mutations in Notch pathway components, particularly in the NOTCH1 and NOTCH2 receptor and RBPJ genes, have been detected in isocitrate dehydrogenase (IDH) mutant gliomas." (PMID 36358826, 2022).
glioma (continued). "Additionally, significantly enhanced binding between the RBPJ protein and the proposed ORC6 promoter region was detected in glioma tissues and cells." (PMID 38971772, 2024). "We performed RIN1 treatment of our glioma cells, and while RIN1 did not have a noticeable effect on RBPJ expression, RIN1-treated XIII, XIII-WT, and XVII cells exhibited significantly reduced cell viability." (PMID 32647372, 2020).
glioblastoma (9 papers, 2013 to 2025). The most malignant astrocytic tumor (WHO grade IV). "RBPJ, a crucial TF in Notch signaling was found to promote glioblastoma progression through the IL-6/STAT3 axis in vitro." (PMID 40660393, 2025). "RBPJ, a key transcription factor in the Notch pathway, can enhance the migration and invasion capacity of glioblastoma cells." (PMID 38672496, 2024). "The proximal TNC promoter contains a crucial RBPJκ binding element and in glioblastoma, TN-C was shown to be trans-activated by Notch2 signaling in an RBPJκ-dependent manner." (PMID 35785162, 2022). "An additional mechanism by which Notch mediates tumor aggressiveness is by the induction of Tenascin-C – an extracellular glycoprotein which correlates with malignancy in glioblastoma and other cancers – by the Notch canonical co-activator RBPJκ." (PMID 23451269, 2013). "As molecular switches in regulating the notch response, transcription factor RBPJ involves in the regulation of the progression of a variety of tumors, such as colorectal cancer, lung cancer, hepatocellular carcinoma, glioblastoma, and prostate cancer." (PMID 35879975, 2022).
hepatocellular carcinoma (9 papers, 2010 to 2025). A malignant tumor that arises from hepatocytes. "In vitro and in vivo validation of Cancer Genome Atlas screening results demonstrate that RBPJ is an important factor regulating the function of T cells in hepatocellular carcinoma." (PMID 36717584, 2023). "To assess the effect of RBPJ deficiency on hepatic type 1 ILC function, we chose a model of hepatocellular carcinoma by injection a Hepa1–6 mouse liver cancer cell line." (PMID 29930552, 2018). "In contrast, knocking down RBPJ and thus interfering with the Notch signaling pathway not only failed to inhibit tumor growth, but also accelerated tumor proliferation in a hepatocellular carcinoma." (PMID 34178692, 2021).
Adams-Oliver syndrome (8 papers, 2013 to 2025). Adams-Oliver Syndrome (AOS) is a rare disorder characterized by the combination of congenital limb abnormalities and scalp defects, often accompanied by skull ossification defects. "We show that RBPJ variants associated with Adams-Oliver Syndrome act as dominant-negative proteins that reduce Notch1 signaling in the endothelium to cause pathogenesis." (PMID 41055965, 2025). "Impaired RBPJ-DNA binding as in Adams-Oliver-Syndrome affect both target site association and dissociation, while impaired cofactor binding mainly alters association and unspecific binding." (PMID 39893191, 2025). "In humans, RBPJ variants have been linked to Adams-Oliver syndrome (AOS), a rare autosomal dominant disorder characterized by scalp, cranium, and limb defects." (PMID 35951645, 2022). "Intriguingly, the E137 Su(H) residue corresponds to E63 in human RBPJ, which was found to be encoded by a missense variant (E63G) in a family with Adams Oliver Syndrome (AOS)." (PMID 35951645, 2022). "Human genetic studies previously revealed that Adams Oliver Syndrome (AOS) is associated with autosomal dominant alleles in the NOTCH1, DLL4, and RBPJ genes." (PMID 35951645, 2022).
colorectal cancer (7 papers, 2020 to 2026). A primary or metastatic malignant neoplasm that affects the colon or rectum. "Experimental research has shown that knockout of circ_0001535 inhibits the growth of colorectal cancer by upregulating the expression of miR‐433‐3p and downregulating the expression of recombination signal‐binding protein Jκ(RBPJ)." (PMID 40900300, 2025). "As formerly reported, DAB1 could be transcriptionally promoted in colorectal cancer via RBPJ, an important transcriptional factor of NOTCH pathway." (PMID 32415085, 2020). "In colorectal cancer (CRC) cell lines, RIP140 positively regulated HES1 gene expression at the transcriptional level via a recombining binding protein suppressor of hairless (RBPJ)/neurogenic locus notch homolog protein 1 (NICD)‐mediated mechanism." (PMID 38459621, 2024).
lung carcinoma (7 papers, 2010 to 2023). "Our immunoprecipitation–western blotting experiment confirmed that NICD1 bound to RBPJ in lung cancer cells." (PMID 27456471, 2016). "It has been proven that the Notch receptor and ligand have abnormal expression in various types of lung cancer, and the transcription factor RBPJ is a component of the Notch signaling pathway." (PMID 33138076, 2020).
liver cancer (6 papers, 2018 to 2025). An epithelial or non-epithelial malignant neoplasm that arises from the liver. "Supporting this, another study identified recombination signal binding protein for immunoglobulin kappa J region (RBPJ) binding to a region relatively close to the YY1 binding sites, specifically in hepatocytes and liver cancer cells." (PMID 34809697, 2021). "Furthermore, we explored the clinical relationship between RBPJ and DAPK3 and found that there was a positive correlation between RBPJ and DAPK3 in renal clear cell carcinoma, bladder cancer, pancreatic cancer, and liver cancer." (PMID 35368029, 2022).
pancreatic cancer (6 papers, 2020 to 2024). "Protein-bound polysaccharide-K (PSK) was found to reduce RBPJ expression and block RBPJ-induced invasiveness and proliferation under hypoxic conditions by inhibiting matrix metalloproteinase expression in pancreatic cancer cells." (PMID 33329729, 2020). "The expression of RBPJ is ubiquitous, also clearly detectable in human pancreatic tissue, PDAC and pancreatic cancer cell lines." (PMID 34638511, 2021). "Specifically, RBPJ (ranked 8th in patient TCGA-BH-A0BZ and 9th in patient TCGA-BH-A0BJ) was reported as a potential oncogene in certain cancers and the upregulation of RBPJ can induce pancreatic cancer, although RBPJ has not been listed in NGC and CGC under current version yet." (PMID 38254011, 2024).